DAPK1 (death associated protein kinase 1)
Diseases named in the same sentence as DAPK1 in open-access papers (continued):
Sharing a sentence is not in itself a finding about the gene and the disease.
colorectal tumors (5 papers, 2015 to 2022). "As recently published, the combination of the CAM model and MPM allowed for the visualization of tumor growth into a collagen-rich ECM for colorectal tumor cells with death-associated protein kinase 1 (DAPK1) gene knockout." (PMID 35625969, 2022). "In this study, we firstly report a novel DAPK1-mediated network associated with metastatic potential of colorectal tumors." (PMID 31772156, 2019). "To mirror-image the loss of DAPK1 protein observed at tumor invasion front of colorectal tumors, we first established CRISPR/Cas9-driven DAPK1 ko HCT116 cell lines using two different single guide RNAs (sgRNA1 and 2)." (PMID 31772156, 2019). "In this study, we investigated the ECM remodeling potential of DAPK1 in colorectal tumor cells." (PMID 35625969, 2022). "Here, we used the chorioallantoic membrane (CAM) assay as a natural, collagen-rich tissue model in combination with all-optical experimental access by multiphoton microscopy (MPM) to study the ECM remodeling potential of colorectal tumor cells with and without DAPK1 in situ and even in vivo." (PMID 35625969, 2022).
endometrial adenocarcinoma (5 papers, 2012 to 2024). "Genistein has also been shown to interact with death-associated protein kinase 1 (DAPK1) and has been suggested as a potential treatment for endometrial adenocarcinomas." (PMID 36430712, 2022).
pancreatic cancer (5 papers, 2011 to 2021). "In pancreatic cancer, the level of DAPK1 was significantly down-regulated, and increased DAPK1 expression inhibited the migration and invasion of pancreatic cancer cells." (PMID 34422899, 2021). "Up-regulation of DAPK1 alleviates the malignant behavior of pancreatic carcinoma through the PI3K/Akt and ERK pathway." (PMID 28934284, 2017). "MiR-182 was highly expressed in pancreatic cancer and confirmed to directly target DAPK1." (PMID 34422899, 2021). "We investigated methylation levels at selected CpG sites in the CpG rich regions at the promoter regions of p16, RARbeta, TNFRSF10C, APC, ACIN1, DAPK1, 3OST2, BCL2 and CD44 in the blood of 30 pancreatic tumor patients and in the blood of 49 matching controls." (PMID 22629410, 2012).
amyloid (4 papers, 2021 to 2026). "In summary, these findings demonstrate that degrading DAPK1 via a PROTAC strategy simultaneously mitigates both amyloid and tau pathology, indicating that CP1 is an effective candidate for disease-modifying therapy." (PMID 42157943, 2026). "Since the activation of DAPK1 function could contribute to the amyloidogenic processing of APP and the hyperphosphorylation of tau 44, DAPK1 may serve as an important therapeutic target for the simultaneous control of both amyloidosis and tauopathy in AD." (PMID 35002518, 2022). "Although the role of DAPK2 in amyloidosis in unknown, another family member, DAPK1, promotes the phosphorylation and amyloidogenic processing of APP." (PMID 30361487, 2021).
chronic myeloid leukemia (4 papers, 2015 to 2024). "In the present study, DAPK1 methylation was investigated in chronic myeloid leukemia patients (n=43) using bisulfite conversion followed by methylation-specific polymerase chain reaction." (PMID 25435999, 2015). "Therefore in this study, we determined the DNA methylation status at CpG dinucleotides of DAPK1, RASSF1, p16INK4, p14ARF, RIZ1 and SOCS1 in concert with disease progression, imatinib response and overall survival in chronic myelogenous leukaemia." (PMID 35421941, 2022).
Hypertension (4 papers, 2018 to 2025). The presence of chronic increased pressure in the systemic arterial system. "Moreover, our recently published study demonstrates that DAPK1 promotes hypertension by enhancing vasoconstriction through myosin light chain phosphorylation, and its inhibition effectively attenuates hypertension and associated vascular damage." (PMID 40918124, 2025).
oral squamous cell carcinoma (4 papers, 2013 to 2025). "The aim of this study was to investigate the immunohistochemical expression of DAPK-1 in oral leukoplakia (OL) and oral squamous cell carcinoma (OSCC)." (PMID 40104466, 2025). "In particular, our study focused on the DAPK-1 expression in oral leukoplakia (OL) and oral squamous cell carcinoma (OSCC) compared to the normal oral mucosa (NOM)." (PMID 40104466, 2025). "The present study aims to investigate the vascular endothelial expression of the DAPK-1 in paraffin-embedded tissue samples of oral leukoplakia, oral squamous cell carcinoma, and oral lichen planus." (PMID 39081443, 2024).
osteosarcoma (4 papers, 2015 to 2023). A usually aggressive malignant bone-forming mesenchymal neoplasm, predominantly affecting adolescents and young adults. "Among them, MAN2B1, P4HA2, ANPEP, BCAT1, CTSS, and DAPK1 were significantly correlated with the prognosis of patients with osteosarcoma." (PMID 37457661, 2023).
renal cell carcinoma (4 papers, 2006 to 2021). "In renal cell carcinoma (RCC), the expression of DAPK1 was decreased." (PMID 34422899, 2021). "Renal cell carcinoma patients had median NIM levels of 51% in the younger group and 53% in the older group for APAF-1, the corresponding levels being 2 and 2%, respectively for DAPK-1." (PMID 17133271, 2006).
tauopathy (4 papers, 2020 to 2025). Neurodegenerative disorders involving deposition of abnormal tau protein isoforms (tau proteins) in neurons and glial cells in the brain. "It is worthwhile to validate the pathological relevance of DAPK1/SENP1 axis using transgenic mouse models of tauopathy in the future." (PMID 41272902, 2025). "MARK2 knockdown has no impact on DAPK1-induced tau hyperphosphorylation, but the MARK2-induced tau phosphorylation and microtubule destabilization are potentiated by DAPK1 in neurons as DAPK1 overexpression enhances MARK2 activity in tauopathy." (PMID 38195518, 2024). "Few compounds belonging to the proposed series were reported as CSF1R/DAPK1 inhibitors as anti-tauopathies." (PMID 31809612, 2020). "Besides, the expression of DAPK1 is also elevated in brains of transgenic mice for tauopathy." (PMID 41272902, 2025). "DAPK1-mediated SENP1 phosphorylation and degradation promote tau SUMOylation, exacerbating tau pathology and cognitive dysfunction in tauopathy." (PMID 41272902, 2025). "The influence of DAPK1 on SENP1 expression, tau SUMOylation and phosphorylation was analyzed using a mouse model for tauopathy by overexpressing human tau in the hippocampal CA3 region, as well as using human AD brain tissues." (PMID 41272902, 2025).
triple-negative breast carcinoma (4 papers, 2017 to 2022). An invasive breast carcinoma which is negative for expression of estrogen receptor (ER), progesterone receptor (PR), and human epidermal growth factor receptor 2 (HER2). "Interestingly, DAPK1 Knockdown or inhibition significantly suppressed the growth of the HCC1143, HCC1937, HCC1954 triple-negative breast cancer (TNBC) cell lines by 80–90% suggesting the development of DAPK1 inhibitors to target TNBC." (PMID 31809612, 2020).
cervical disease (3 papers, 2018 to 2023). "Using prospective time-to-event data, we detected associations between CADM1-, DAPK1-, PAX1-, and RARB-related CpGs and cervical disease progression, and we identified novel progression-associated CpGs." (PMID 37932662, 2023). "DAPK1 combined with the other two showed a significantly positive correlation with cervical disease grade as well." (PMID 29850477, 2018). "The promoter methylation statuses of DAPK1, MGMT, and RARB were positively correlated with the cervical disease grades, respectively." (PMID 29850477, 2018).
depression (3 papers, 2018 to 2022). "The interaction of death-associated protein kinase 1 (DAPK1) with the 2B subunit (GluN2B) C-terminus of N-methyl-D-aspartate receptor (NMDAR) plays a critical role in the pathophysiology of depression and is considered a potential target for the structure-based discovery of new antidepressants." (PMID 30463177, 2018). "High expression of DAPK1 and phosphorylated NR2B at Ser1303 are key components in the pathophysiology of depression." (PMID 34239362, 2021).
inflammatory bowel disease (3 papers, 2015 to 2022). A spectrum of small and large bowel inflammatory diseases of unknown etiology. "The other four candidate targets with a link to autoimmunity are DAPK1 (inflammatory bowel disease), MST4 (Grave’s disease), PXK (systemic lupus erythematosus), and IRAK3 (rheumatoid arthritis) (for literature evidence check S1 Table)." (PMID 32459810, 2020).
injury (3 papers, 2013 to 2022). Damage inflicted on the body as the direct or indirect result of an external force, with or without disruption of structural continuity. "Therefore, the development of small molecule inhibitors for DAPk1 is an attractive treatment option for perinatal brain injury since they have reduced adverse effects, can easily be administered and screened for specificity and capacity of binding with a target." (PMID 23880846, 2013).
laryngeal squamous cell carcinoma (3 papers, 2014 to 2021). A squamous cell carcinoma that arises from the larynx. "For example, in a cohort of 41 laryngeal squamous cell carcinomas, 76% (31/41) of the samples demonstrated methylation of DAPK1 and 32% (13/41) of the samples demonstrated methylation of RASSF1A." (PMID 25859283, 2014).
memory impairment (3 papers, 2022 to 2024). "Activation of DAPK1 could result in memory loss, and inhibition of DAPK1 could attenuate memory impairment in mice." (PMID 38752632, 2024). "Moreover, activation of DAPK1 contributes to learning and memory deficiency, whereas inhibition of DAPK1 through deletion of the DAPK1 kinase domain ameliorates learning and memory impairment in mice." (PMID 37047515, 2023). "However, DAPK1 knockdown and catalytic activity inhibition decrease inflammation and ameliorate memory impairment." (PMID 37047515, 2023). "Then, we found that neuronal apoptosis and NR2B phosphorylation after TBI could be alleviated by knockdown DAPK1 expression in the cortex, which further moderated motor and memory impairment in mice." (PMID 35783103, 2022).
ovarian endometriosis (3 papers, 2017 to 2025). A non-neoplastic disorder characterized by the growth of endometrial tissue in the ovaries. "In a previous study, miR-191-5p inhibited TNF-α-induced apoptosis of ovarian endometriosis and endometrioid carcinoma by targeting DAPK1." (PMID 40064799, 2025). "However, in the previous study, DAPK1 was confirmed by a luciferase reporter worked as a downstream molecular of miR-191-5p in ovarian endometriosis and endometrioid carcinoma." (PMID 40064799, 2025).
renal carcinoma (3 papers, 2019 to 2023). A carcinoma arising from the epithelium of the renal parenchyma or the renal pelvis. "Strikingly enough, a detailed analysis of the mRNA and protein expression profile of DAPk1 in various tumor cell lines, including bladder, breast and renal carcinomas, led to the discovery of loss of DAPk1 expression." (PMID 30783518, 2019).
acute promyelocytic leukemia (2 papers, 2017 to 2021). An aggressive form of acute myeloid leukemia (AML), characterized by arrest of leukocyte differentiation at the promyelocyte stage, due to a specific chromosomal translocation t(15;17) in myeloid cells. "In a recent study of 60 acute promyelocytic leukemia (APL) primary samples at diagnosis, methylation of DAPK1, miR-34a and -34b/c were tumor-specific in APL." (PMID 28153026, 2017).
anal carcinoma (2 papers, 2012 to 2015). "Increasing methylation levels of DAPK1 have also been reported in anal cancer progression, suggesting that epigenetic alterations of DAPK1 are common across HPV-associated cancers." (PMID 25826459, 2015).
aneurysm (2 papers, 2009 to 2023). Bulging or ballooning in an area of an artery secondary to arterial wall weakening. "Since vascular smooth muscle apoptosis and inflammation have been demonstrated to be important mechanisms in human AAA, upregulation of Dapk1 and Cd59 may be relevant to the predilection of the suprarenal aorta to aneurysm formation in ApoE-/- mice." (PMID 19580648, 2009).
Anxiety (2 papers, 2022 to 2025). Intense feelings of nervousness, tension, or panic often arise in response to interpersonal stresses. "However, DAPK1 ablation alleviated anxiety-like behavior as evidenced by an increase in the time spent in open arm for the DAPK1-KO + hTau mice." (PMID 41272902, 2025). "However, the distance traveled in the central zone was increased in hTau + C6 group, suggesting that DAPK1 inhibition attenuated hTau-induced anxiety-like behavior." (PMID 41272902, 2025).
astrocytoma (2 papers, 2004 to 2011). "Seventeen genes (ABL, APC, APAF1, BRCA1, CSPG2, DAPK1, hMLH1, LKB1, PTEN, p14ARF, p15INK4b, p27KIP1, p57KIP2, RASSF1C, RB1, SURVIVIN, and VHL) displayed a uniformly unmethylated pattern in all the astrocytoma and non-astrocytoma tissues examined." (PMID 15367334, 2004).
atherosclerosis (2 papers, 2015 to 2025). A disease characterized by the build-up of fatty material and calcium deposition in the arterial wall resulting in partial or complete occlusion of the arterial lumen. "MMP9, DAPK1, and P2RY13 tracked by flourishing AI nomogram (LASSO, RF, and SVM) were negatively related with Macrophages M1, translating as PCOS-mediated hub genes in atherosclerosis, with the latent pathogenesis lies in inflammatory response and immunity." (PMID 40549330, 2025).
chronic kidney disease (2 papers, 2014 to 2025). Impairment of the renal function secondary to chronic kidney damage persisting for three or more months. "DAPK1 is activated by signals including TGFβ, which plays multiple roles in chronic kidney disease (CKD)." (PMID 24906443, 2014).
cognitive decline (2 papers, 2023 to 2025). "Death-associated protein kinase 1 (DAPK1) is a protein kinase that phosphorylates serine and threonine residues at protein sites, and our group demonstrated that DAPK1 phosphorylates the Tau protein, leading to cognitive decline in the mouse models of AD." (PMID 40332373, 2025).
diabetes (2 papers, 2019 to 2025). "Here novel insights into the molecular mechanisms are provided underlying DE, and the therapeutic potential of targeting DAPK1 and Ntn1 is highlighted to alleviate diabetes-associated central nervous system complications." (PMID 40787892, 2025).
fibrous histiocytoma (2 papers, 2014 to 2015). "Four Roco proteins are identified in vertebrates, called leucine-rich repeat (LRR) kinase 1 (LRRK1), LRRK2, death-associated protein kinase 1 (DAPK1) and malignant fibrous histiocytoma amplified sequences with leucine-rich tandem repeats (MASL)." (PMID 26310572, 2015). "Four Roco proteins are identified in vertebrates, called LRRK1, LRRK2, death-associated protein kinases-1 (DAPK1), and malignant fibrous histiocytoma amplified sequences with leucine-rich tandem repeats 1 (MASL)." (PMID 24847205, 2014).
gynecological cancer (2 papers, 2022 to 2025). "To this end, we screened the expression patterns of different putative candidate genes, including DAPK1, in gynecological cancer cell lines and primary cancer cells." (PMID 40563561, 2025).
Huntington disease (2 papers, 2020 to 2025). Huntington disease (HD) is a rare neurodegenerative disorder of the central nervous system characterized by unwanted choreatic movements, behavioral and psychiatric disturbances and dementia. "Inhibition of DAPK1 also normalized extrasynaptic GluN2B phosphorylation on Ser1303 and surface expression in cortico-striatal neurons, and prevented striatal spine loss in cortico-striatal co-cultures isolated from YAC128 HD mice, a model of Huntington’s disease." (PMID 40029461, 2025).
malaria (2 papers, 2014 to 2018). Malaria is a serious and sometimes fatal disease caused by a parasite that commonly infects a certain type of mosquito which feeds on humans. "Four proteins (CA2, CKB, CKM, DAPK1) were only found to be associated with severe compared to mild malaria." (PMID 30442134, 2018). "In the severe malaria groups, intracellular proteins (TIPIN, MSRB1), components of glucose metabolism (ADSSL1, DNPEP1) and an inflammatory protein (DAPK1) had increased levels, further confirming observations made above with the ‘targeted array’." (PMID 24743550, 2014).
metastasis (2 papers, 2011 to 2014). The spread or migration of cancer cells from one part of the body (where they first appeared) to another. "Of note, there was a trend toward an association between methylation of CALCA and DAPK1 and invasion or adhesion and lymph node metastasis, suggesting that aberrant methylation of these genes is associated with oncologic outcomes of NSCLC patients." (PMID 21507233, 2011). "DAPK1 is a positive regulator of cell apoptosis, and has been found to correlate with poorly differentiated tumors and lymph node metastasis." (PMID 25202403, 2014).
mouth neoplasm (2 papers, 2014 to 2022). "In comparison, in 47 oral cavity tumors, a frequency of 30% for DAPK1 and 38% for RASSF1A were reported." (PMID 25859283, 2014).
myocardial infarction (2 papers, 2022 to 2025). Gross necrosis of the myocardium, as a result of interruption of the blood supply to the area, as in coronary thrombosis. "DAPK1 has emerged as a significant player in the pathogenesis of heart disease, particularly in the context of myocardial infarction and heart failure." (PMID 40918124, 2025). "The results of TTC staining showed that after inhibition of DAPK1, the range of myocardial infarction in rats was reduced." (PMID 35082934, 2022). "We found that with the increase of myocardial infarction time, the expression of DAPK1 in myocardial tissue gradually increased." (PMID 35082934, 2022). "In a study using a rat model of acute myocardial infarction (AMI), the DAPK1 expression was significantly higher in AMI rats compared to controls." (PMID 40918124, 2025). "Myocardial infarction markers LDH and CK also decreased with the inhibition of DAPK1." (PMID 35082934, 2022).
Obesity (2 papers, 2017 to 2025). Accumulation of substantial excess body fat. "The results of this study indicate that plasma proteins such as TPST1, ROR1, and DAPK1 may mediate the relationship between obesity and allergic asthma." (PMID 39893495, 2025).
oligodendroglioma (2 papers, 2009 to 2014). A well-differentiated (WHO grade II), diffusely infiltrating neuroglial tumor, typically located in the cerebral hemispheres. "Other genes hypermethylated in oligodendrogliomas include the tumor suppressors CDKN2A, CDKN2B and RB1, as well as DAPK1 (death-associated protein kinase 1), ESR1 (estrogen receptor 1), THBS (thrombospondin 1) and TIMP3 (tissue inhibitor of metalloproteinase 3)." (PMID 19333441, 2009).
polycystic ovary syndrome (2 papers, 2020 to 2021). A disorder that manifests as multiple cysts on the ovaries. "miR-141 affects the MAPK signaling pathway by regulating DAPK1 expression, which leads to the development of polycystic ovary syndrome (PCOS)." (PMID 34763659, 2021). "miR-141 was shown to be significantly upregulated in OC cell lines and advanced metastatic OC, and can inhibit GC apoptosis by targeting DAPK1 through the MAPK signaling pathway, leading to the development of polycystic ovary syndrome (PCOS)." (PMID 32228439, 2020).